HKDC1 (hexokinase domain containing 1)
Diseases named in the same sentence as HKDC1 in open-access papers (continued):
Sharing a sentence is not in itself a finding about the gene and the disease.
cancer (continued). "Moreover, therapeutic approaches targeting HKDC1 are expected to improve cancer treatment outcomes by intervening in tumor metabolism and enhancing the tumor immune microenvironment, making it an important focus for future cancer metabolic interventions and immunotherapy." (PMID 41049000, 2025). "Hexokinase domain component 1 (HKDC1) is reported to play a critical role in the maintenance of glucose homeostasis and there is increasing evidence to suggest that its overexpression may contribute to several types of cancers." (PMID 36855062, 2023). "As cancer cells in the synthetic (S) phase of the cell cycle need ATP to prepare the cells for division, a lack of ATP might result in cell-cycle arrest as observed in HKDC1-KO cells, however, this needs further mechanistic investigation." (PMID 35902556, 2022). "As HKDC1 is highly expressed in LC cells, but only to a minimal degree in hepatocytes under normal conditions, targeting HKDC1, specifically its interaction with the mitochondria, may represent a highly selective approach to target cancer cells in LC." (PMID 35902556, 2022). "Finally, our work clearly shows that HKDC1 is involved in progression of LC, but it remains to be investigated whether it is also essential for cancer metastasis." (PMID 35902556, 2022). "Furthermore, it was plausible that HKDC1 could be a promising potential therapeutic target for numerous kinds of carcinomas." (PMID 33991070, 2021). "This study indicates that HKDC1 may be a new target for cancer therapy." (PMID 31058090, 2019). "Mechanistically, HKDC1 enhances glycolytic flux through modulation of the AMPK/mTOR signaling pathway, thereby supporting cancer cell metabolism and growth." (PMID 41049000, 2025). "HKDC1 significantly influences the tumor microenvironment (TME), a critical determinant of cancer progression." (PMID 41049000, 2025). "HKDC1 drives key oncogenic processes, inlcuding cell proliferation, migration, invasion, apoptosis and EMT in various cancer types." (PMID 41049000, 2025). "The rationale for the selection of the genes, HKDC1, RAB3IL1, RAB39B, FTH1, and FAM213A, is their potential pro-tumorigenic roles in other cancer types." (PMID 37082446, 2023). "We recently discovered a novel fifth HK, hexokinase domain containing 1 (HKDC1), which has been shown to be overexpressed in certain cancers compared to healthy tissue, and most significantly in LC, where it interacts with the mitochondria." (PMID 35902556, 2022). "We also conducted IP/WB to evaluate the potential effect of HKC8 on HKDC1/VDAC1 interaction in different cells, including normal HMECs cells and two kinds of cancer cell lines, HANK1 and SW480." (PMID 32203147, 2020). "Although the splicing events of these genes were not reported previously, their gene expression level was linked to tumorigenesis or prognosis of CRC (SERPINA1) or other cancer types (ARHGEF9, CHEK1, HKDC1)." (PMID 32503434, 2020). "Despite extensive literature searches, no comprehensive pan-cancer analysis of HKDC1 from a holistic viewpoint has been reported, underscoring the need for a global investigation into its role in tumorigenesis." (PMID 40124623, 2025). "The fifth member of the family, hexokinase domain-containing protein-1 (HKDC1) is a widely expressed novel HK that plays a role in glucose homeostasis and is involved in the progression of several pathological conditions including cancer." (PMID 36337735, 2022). "In this study, we uncovered an unexpected function of HKDC1 in regulating PD-L1-induced immune evasion independent of its hexokinase activity in glucose metabolism, thus providing insights into the role of metabolic enzymes in anti-cancer immunity." (PMID 38351096, 2024). "However, a limitation in our mouse model is that our chronic overexpression of HKDC1 stopped at 16 weeks and is perhaps was not enough time to produce a full metabolic switch towards cancer metabolism." (PMID 37198225, 2023).
cancer (continued). "The findings indicated that HKDC1 transcripts frequently served as negative prognostic indicators for both OS and DSS in multiple cancer types." (PMID 40124623, 2025). "Increased HKDC1 levels were further explained by a formation of a negative feedback loop to maintain high levels of glycolysis in the absence of KRAS signaling, a common feature of cancer cells." (PMID 28039486, 2017). "Furthermore, differences were observed in the expression of several non-canonical and/or embryonic isoforms (HK3, HKDC1, ALDA, GADPH-S, PGK2, and PKM) between patients and controls, as well as in the expression of isoforms considered hallmarks of cancer, such as HK2." (PMID 41009047, 2025).
tumor (33 papers, 2018 to 2025). "The association between HKDC1 expression, immune cell infiltration, and the existence of immune checkpoints suggests a possible connection between the tumor microenvironment and HKDC1, alongside tumor advancement." (PMID 40124623, 2025). "Our investigation centered on evaluating the differential expression and prognostic significance of HKDC1, while also examining its connections to tumor heterogeneity, mutation profiles, and RNA modifications." (PMID 40124623, 2025). "Given the close association between cell cycle dysregulation and tumor cell proliferation and the counteracting role of apoptosis, we investigated the potential relationship between HKDC1, cell cycle progression, and apoptosis in CRC cells." (PMID 40209953, 2025). "The examination revealed that older age (HR= 1.026, p = 0.015), higher tumor grade (HR= 1.383, p = 0.028), and increased HKDC1 expression (HR= 1.289, p = 0.001) were strongly linked to unfavorable prognosis." (PMID 38434978, 2024). "Collectively, these results illustrated that HKDC1 association with Actin filament is necessary for its promotion of tumor immune escape." (PMID 38351096, 2024). "However, while WT ApcMin/+ tumor organoids were completely resistant to cell death, HKDC1 deletion restored cell death susceptibility." (PMID 40110992, 2025). "Gene set enrichment analysis (GSEA) further substantiates the idea that HKDC1 may play a role in several critical pathways and biological processes associated with neoplasm." (PMID 40124623, 2025). "Nevertheless, our findings revealed a degree of uncertainty regarding the exact prognostic function of HKDC1, as it exhibited an association with unfavorable prognosis in certain tumor types while serving as a protective factor in others, specifically in THYM and LGG." (PMID 40124623, 2025). "Both in vitro and in vivo, HKDC1 overexpression accelerates proliferation, metastasis, and tumor growth while reducing survival 27,28." (PMID 41049000, 2025). "HKDC1 serves as a critical regulator of tumor metabolism, particularly through glycolytic pathway activation." (PMID 41049000, 2025). "In vivo, HKDC1 knockdown inhibited tumor growth, while overexpression accelerated tumor progression." (PMID 40209953, 2025). "The study further demonstrated that the combination of inhibiting HKDC1 and anti-PD-1 /PD-L1 antibodies can significantly enhance the anti-tumor response of CD8+ T cells." (PMID 40124623, 2025). "To date, researchers have gained some understanding of the role and mechanism of HKDC1 in tumours and inflammatory diseases 25,26; however, its role in the kidneys has not yet been reported." (PMID 40520008, 2025). "Notwithstanding these compelling discoveries, the function of HKDC1 in the context of tumor biology is still inadequately examined, with a limited number of thorough studies assessing its association with different types of tumors." (PMID 40124623, 2025). "RCOR1 overexpression counteracted the suppression of CRC cell proliferation and migration caused by HKDC1 knockdown, while RCOR1 knockdown inhibited the tumor-promoting effects of HKDC1 overexpression." (PMID 40209953, 2025). "The amalgamation of samples from both the GTEx and TCGA databases produced persuasive evidence of a notable escalation in HKDC1 expression across diverse tumor types." (PMID 40124623, 2025). "To directly assess HKDC1's role in intestinal carcinogenesis in vivo, we phenotyped tumor‐bearing ApcMin/+‐Hkdc1∆IEC mice." (PMID 40110992, 2025). "Future research should focus on elucidating HKDC1's broader interactions within tumor biological networks and its crosstalk with complementary metabolic pathways." (PMID 41049000, 2025). "Elevated HKDC1 correlates with increased cell division and diminished apoptotic activity, crucial for tumor growth and metastasis." (PMID 41049000, 2025).
tumor (continued). "This study seeks to conduct a thorough investigation of HKDC1’s potential functions across thirty-three different tumor types, utilizing data obtained from The Cancer Genome Atlas (TCGA)." (PMID 40124623, 2025). "Currently, research on the role of hexokinase domain-containing protein-1 (HKDC1) in neoplasm metabolism remains sparse." (PMID 40124623, 2025). "Overall, the evidence supports the idea that HKDC1's role in glucose metabolism, along with its correlation with tumor growth and glycolytic activity, underscores its potential for enhancing diagnostic capabilities." (PMID 41049000, 2025). "By orchestrating signaling cascades, such as AMPK/mTOR, Wnt/β-catenin, and AKT/AMPK, and reprogramming metabolic pathways including glycolysis, lipid metabolism, and the tricarboxylic acid cycle, HKDC1 enhances tumor aggressiveness and chemoresistance." (PMID 41049000, 2025). "In summary, the results of this investigation provide valuable insights into the diverse roles of HKDC1 in tumor regulation, highlighting several critical aspects." (PMID 40124623, 2025). "Its expression on the mitochondrial membrane and interaction with VDAC1 affect glucose uptake and tumor growth, suggesting HKDC1 as a potential therapeutic target across malignancies." (PMID 41049000, 2025). "An increasing volume of research suggests that HKDC1 demonstrates distinct expression profiles in tumor tissues and plays crucial roles in multiple facets of tumor biology." (PMID 40124623, 2025). "To further corroborate these findings, we performed a xenograft transplantation model, where WT and HKDC1‐deficient Caco‐2 cells were subcutaneously injected into the flanks of immunocompromised NSG mice, and tumor growth was monitored over time." (PMID 40110992, 2025). "In HBV-infected cells, OIP5-AS1 downregulation resulted in upregulation of HKDC1, which promotes glycolysis and accelerates cell cycle progression, thereby driving tumor growth and also it showed a reduction in expression in HBV-positive HCC patients." (PMID 40625740, 2025). "In this work, we use clinical HCC samples and a series of HCC preclinical models to demonstrate the role of HKDC1 in promoting tumor immune evasion by coupling STAT1 activation with the cellular cytoskeleton to enhance PD-L1 expression in HCC cells." (PMID 38351096, 2024). "Decreased PD-L1 protein levels were also observed in YAP5SA-induced HCC tumor tissues of HKDC1 KO mice compared with the WT group." (PMID 38351096, 2024). "To explore how HKDC1 regulates CD8+ T cell-dependent tumor immune evasion, we detected the mRNA levels of immune checkpoint markers in IFNγ-stimulated Hep3B cells expressing shHKDC1s or NTC." (PMID 38351096, 2024). "A positive correlation was observed between the expression of HKDC1 and three different types of tumor-initiating cells (TICs), namely resting memory CD4 T cells, M0 macrophages, and M1 macrophages." (PMID 38434978, 2024). "As a result, HKDC1 inhibition and low dose PD-1 antibodies (αPD-1low, 25 μg/mouse) each modestly inhibited tumor growth, while siHKDC1 further enhanced the antitumor effects of αPD-1." (PMID 38351096, 2024). "Here we show that hexokinase domain component 1 (HKDC1) promotes tumor immune evasion in a CD8+ T cell-dependent manner by activating STAT1/PD-L1 in tumor cells." (PMID 38351096, 2024). "qPCR results showed that HKDC1 was expressed at substantially higher levels in tumor cells compared to other cells." (PMID 38351096, 2024). "Like the other four isozymes, HKDC1 seems to play an important role in mediating glucose metabolism for tumor development." (PMID 38434978, 2024). "Our data establish a previously unappreciated mechanism by which HKDC1 couples the cytoskeleton to STAT1/PD-L1-mediated tumor immune evasion." (PMID 38351096, 2024). "HKDC1 expression was shown to have significantly increased expression levels in GC tumor tissues from two datasets." (PMID 37153834, 2023).
tumor (continued). "HKDC1 is one of the most prevalent glyGenes in GC tumor tissues and cells, as seen in the Venn diagram." (PMID 37153834, 2023). "Furthermore, we observed that co-treatment of LF could neutralize the differential expression of NT5DC3 and HKDC1 induced by glucose concentration (comparing with control, P < 0.05), suggesting the important mechanism underlying LF’s anti-tumor activity via the regulation of NT5DC3 and HKDC1." (PMID 36855062, 2023). "Decreased transcription (by 3.2-fold) of Hkdc1 gene, a newly identified isoform of hexokinase, is evident in KO tumor as well." (PMID 34685767, 2021). "Our results suggested that Tf-D-HKC8 peptide-mediated interruption of HKDC1 suppressed tumor growth with overexpression of SOD2 and OGG1 completely and partly reversing this effect, respectively." (PMID 33423158, 2021). "We evaluated the effect of LMP1 on tumor growth through the activation of PGC1β and the HKDC1 interruption-mediated tumor suppression through the generation of ROS in a mouse model." (PMID 33423158, 2021). "We created a schematic model illustrating the LMP1-mediated tumor development through the activation of PGC1β and tumor suppression through the interruption of HKDC1." (PMID 33423158, 2021). "Our results indicate that HKDC1 expression plays a dominant role in regulation of tumor growth in ENKTL cells, while the effect of HK2 is very small." (PMID 32203147, 2020). "To investigate the effect of HKDC1 on LUAD tumor growth in vivo, we performed xenograft growth assays in nude mice." (PMID 32943998, 2020). "We then evaluated the effect of HK2/HKDC1 expression on tumor growth through thymidine incorporation and [3H]-deoxyglucose uptake." (PMID 32203147, 2020). "Recently, a new HK isoform named HK domain component 1 (HKDC1) has been found to be involved with glucose homeostasis and tumor development." (PMID 32203147, 2020). "We showed that HKDC1 is highly upregulated in ENKTL cells and HKDC1 knockdown significantly suppresses ENKTL tumor growth." (PMID 32203147, 2020). "Further in vivo tumor xenograft studies showed that HKDC1 overexpression promoted tumor colony formation and resulted in decreased mouse survival, while HKDC1 knockdown reversed this effect." (PMID 31058090, 2019). "Our results suggest that HKDC1 expression is involved with tumor growth and that this effect is modulated by PGC1β, and PGC1β also seems to be involved with some other factors." (PMID 31058090, 2019). "We then investigated the potential effect of HKDC1 expression in the in vivo xenograft tumor development study using treated MCF7 cells." (PMID 31058090, 2019). "Furthermore, we analyzed the relationship between HKDC1 expression and tumor immunity utilizing the TIMER analysis approach." (PMID 40124623, 2025). "In the future, the combined treatment strategy of inhibiting HKDC1 and anti-PD-1 /PD-L1 antibodies has shown significant anti-tumor effects, and may become an important direction of tumor immunotherapy in the future." (PMID 40124623, 2025). "In addition, we analyzed the relationship between HKDC1 expression and clinical traits in CRC patients and found that HKDC1 was closely associated with TNM stage, tumor size, and lymph node metastasis." (PMID 40209953, 2025). "Furthermore, in vitro experiments demonstrated that silencing HKDC1 resulted in a marked reduction in the proliferation, migration, and invasion capabilities of neoplasm cells." (PMID 40124623, 2025). "Both Menin overexpression and HKDC1 knockdown significantly suppressed tumor growth compared to the control group, while the combined Menin-OE+shHKDC1 group exhibited the most pronounced tumor growth inhibition." (PMID 40894906, 2025). "Considering the established links between tumor progression and cell proliferation, invasion, and migration, we hypothesized that HKDC1 may influence CRC cell proliferation and migration." (PMID 40209953, 2025).